KIF23 (kinesin family member 23)
Diseases named in the same sentence as KIF23 in open-access papers (continued):
Sharing a sentence is not in itself a finding about the gene and the disease.
glioma (continued). "KIF23 knockdown significantly inhibits glioma cell proliferation." (PMID 30581678, 2018). "For example, the depletion of KIF23 has been shown to inhibit glioma cell proliferation." (PMID 28061449, 2017). "Taken together, these results imply that KIF23 might be a useful independent prognostic biomarker for glioma patients." (PMID 27013586, 2016). "Additionally, glioma samples with wild-type IDH1 showed higher expression of KIF23 than those with mutant IDH1." (PMID 27013586, 2016). "Finally, functional assay showed that reduction of KIF23 suppressed glioma cell proliferation both in vivo and vitro." (PMID 27013586, 2016). "Very recently, expression analysis also revealed a higher level of KIF23 expression in glioma tissues compared to normal brain tissue and it was demonstrated that siRNA-mediated downregulation of KIF23 expression significantly suppressed glioma cell proliferation in vitro." (PMID 23650552, 2013). "Furthermore, knock-down of the KIF23 gene has been shown to abrogate glioma cell proliferation and tumor growth in vivo." (PMID 24327603, 2013). "In glioma, down-regulation of KIF23 could suppress glioma proliferation both in vivo and in vitro, and glioma patients with high levels of KIF23 expression also tend to show poorer prognosis compared with patients with low KIF23 expression." (PMID 23077581, 2012). "Furthermore, high KIF23 expression also conferred poor survival in glioma patients." (PMID 34017355, 2021). "Similarly, KIF23, as a key regulator of cytokinesis, is also found to be correlated with poor prognosis for patients with hepatocellular carcinoma, glioma, gastric cancer, and non-small-cell lung cancer." (PMID 33061942, 2020). "These analyses indicate that KIF23 might have an essential role in glioma cell proliferation." (PMID 27013586, 2016). "However, the prognostic and molecular features of glioma with KIF23 expression is unknown, and the regulation mechanism of KIF23 is still unclear." (PMID 27013586, 2016). "Furthermore, KIF23 also served as an independent prognostic biomarker in glioma patients." (PMID 27013586, 2016). "The clinical data verified the association of the identified genes (i.e., KIF2C, CCNA2, NDC80, KIF11, KIF23, ANLN, and CENPM) with the targeted therapy response and prognosis of glioma patients." (PMID 31682596, 2019). "We screened the differentially expressed genes from the Chinese Glioma Genome Atlas (CGGA) dataset, and found that KIF23 was significantly differentially expressed among WHO II, III and IV tumor samples." (PMID 27013586, 2016). "However, the prognostic and clinicopathological features of glioma with KIF23 expression was not clear yet." (PMID 27013586, 2016).
gastric cancer (22 papers, 2019 to 2025). A primary or metastatic malignant neoplasm involving the stomach. "In summary, this study aims to identify KIF23 as a diagnostic and immunotherapy response to gastric cancer." (PMID 37483517, 2023). "In future, we will knock down KIF23 in human gastric cell lines and in mouse gastric cancer models, and develop an inhibitor of KIF23 to treat GC models." (PMID 37483517, 2023). "Next, we analyzed the relationship between KIF23 expression and infiltrating immune cells in gastric cancer based on the xCELL algorithm." (PMID 37483517, 2023). "Upregulation of KIF23 increases cell proliferation and worsens prognosis in other malignancies, such as gastric cancer." (PMID 35892849, 2022). "In gastric cancer, the miR-1301-3p/KIF23 axis inhibits gastric cancer cell proliferation, migration, and invasion by knocking down circ_0067934." (PMID 36467881, 2022). "For instance, KIF23 is highly expressed in gastric cancer and is correlated with a worse prognosis of patients." (PMID 35359374, 2022). "Increased expression of the kinesin family member 23 (KIF23) has been verified in gastric cancer (GC) and its upregulation contributes to cell proliferation." (PMID 32365332, 2020). "However, the relationship between KIF23 expression and diagnostic value, immune infiltration, and immunotherapy response remains unclear in gastric cancer(GC)." (PMID 37483517, 2023). "In gastric cancer, KIF23 promotes cancer cells proliferation via direct interaction with Amer1." (PMID 35524313, 2022). "In addition, several studies have illustrated KIF23 participates in the occurrence of multiple cancers, including gastric cancer, bladder cancer, lung cancer and pancreatic ductal adenocarcinoma." (PMID 35524313, 2022). "Knockdown of KIF23 resulted in marked inhibition of proliferation in gastric cancer." (PMID 35892849, 2022). "Moreover, some studies have found that KIF23 promotes the proliferation of gastric cancer cells through the Wnt/β-catenin signaling pathway." (PMID 33754001, 2021). "Moreover, KIF23 was highly expressed in gastric cancer cells and it accelerated the progression of gastric cancer." (PMID 32549756, 2020). "This mutual amplification mirrors feedback loops observed in other cancers, such as the NAT10/SEPT9/HIF-1α axis in gastric cancer glycolysis and the NAT10/KIF23/GSK-3β axis in colorectal cancer progression, underscoring the critical role of NAT10 in sustaining oncogenic signaling networks." (PMID 40999468, 2025). "KIF23 plays a key role in cell proliferation, metabolism, differentiation, metastasis and survival through the activation of PI3K/AKT/mTOR and Wnt/β/Linker protein signaling pathway, and has been demonstrated in cancers such as gastric cancer and diffuse large B-cell lymphoma." (PMID 38818376, 2024).
lung carcinoma (19 papers, 2017 to 2024). "In particular, elevated levels of KIF23 have been associated with adverse outcomes in ovarian, breast, and lung cancers." (PMID 37569592, 2023). "KIF23 overexpression was recently shown in lung cancer, and was associated with a low survival rate in lung cancer patients." (PMID 36408131, 2022). "It was reported that KIF23 expression is high in the majority of primary and metastatic lung cancer tissues or cell lines, and it is associated with poor survival." (PMID 34675265, 2021). "Based on this, some studies further confirmed that RNA interference-mediated KIF23 deletion can effectively inhibit lung cancer cell growth and lung tumor formation in vivo, and induce apoptosis of lung cancer cell lines." (PMID 36408131, 2022). "The requirement of lung cancer cell lines for KIF23 is consistent our recent finding that KIF23 is necessary for lung tumor initiation in vivo." (PMID 29435157, 2018). "KIF23 plays key role in progression of lung cancer, but this gene might play crucial role in pituitary prolactinoma." (PMID 33709028, 2021). "None of the previous studies have examined the survival impact of KIF23 in ACC, although several studies have demonstrated it to be a very promising negative prognostic marker in other solid tumors such as hepatocellular carcinoma and lung cancer." (PMID 38935991, 2024).
colorectal cancer (14 papers, 2020 to 2025). A primary or metastatic malignant neoplasm that affects the colon or rectum. "In other researches, KIF23 p.R671W mutation was detected in one family with colorectal cancer." (PMID 34017355, 2021). "In addition, Cox regression analysis showed that the expression level of KIF23 was an independent risk factor for the overall survival and disease-free survival of colorectal cancer patients." (PMID 33754001, 2021). "The upregulation of KIF23 activates Wnt/β-catenin pathway and more β-catenin is transported into the nucleus which led to colorectal cancer progression." (PMID 40588654, 2025). "For instance, studies have demonstrated that the elevated KIF23 expression in colorectal cancer and pancreatic ductal adenocarcinoma is significantly correlated with shorter overall survival and poorer prognosis." (PMID 41138746, 2025). "The results showed that KIF23 promoted the malignant behavior of colorectal cancer by enhancing the proliferation, migration and invasion of CRC cells." (PMID 33754001, 2021). "This study is the first to explore the clinical characteristics of KIF23 upregulation in colorectal cancer patients and its involvement in the malignant behavior of CRC cells through Wnt/β-catenin signaling." (PMID 33754001, 2021). "Our study demonstrated that KIF23 overexpression predicts poor prognosis in colorectal cancer patients and promotes the proliferation, migration and invasion of colorectal cancer cells through the Wnt/β-catenin signaling pathway." (PMID 33754001, 2021). "NAT10 mediates KIF23 acetylation to promote colorectal cancer progression." (PMID 39640362, 2024). "It was reported KIF23 could activate Wnt/β-catenin signaling pathway in gastric and colorectal cancer, and then we explored whether KIF23 affected Wnt/β-catenin signaling pathway in TNBC." (PMID 35524313, 2022). "Similarly, KIF23 mRNA was significantly upregulated in colorectal cancer compared with paired normal colon tissues (N = 8)." (PMID 33754001, 2021). "Then, we explored the biological function of KIF23 in colorectal cancer." (PMID 33754001, 2021). "To assess whether KIF23 is related to the clinical features of CRC patients, we performed immunohistochemistry on 116 colorectal cancer tissue specimens and scored the expression of KIF23." (PMID 33754001, 2021). "Additionally, NAT10 could increase the expression of KIF23 by up-regulating ac4C modification of KIF23 3′-UTR in colorectal cancer." (PMID 38182571, 2024). "Therefore, monitoring the expression of KIF23 may provide an important reference for clinical diagnosis, treatment and prognosis evaluation of colorectal cancer." (PMID 33754001, 2021). "In colorectal cancer, NAT10 mediates the stability of KIF23 mRNA by binding to its mRNA 3'UTR region and up-regulating its mRNA ac4c modification." (PMID 40588654, 2025). "In colorectal cancer cells, NAT10 was found to enhance the stability of KIF23 mRNA by up-regulating its ac4C modification." (PMID 38459019, 2024). "Therefore, we speculate that KIF23 may play a similar role as KIF20A in colorectal cancer." (PMID 33754001, 2021). "KIF14, KIF18B, KIF23, KIF4A, KNTC1, NCAPG2, and MCM3 regulate chromosomal integrity, mitotic spindle formation, and DNA replication, processes that are frequently dysregulated in colorectal cancer." (PMID 40405535, 2025). "In colorectal cancer, NAT10 facilitates tumor progression by ac4C modification of KIF23 mRNA." (PMID 38243170, 2024).
hepatocellular carcinoma (13 papers, 2013 to 2025). A malignant tumor that arises from hepatocytes. "In search for genes associated with hepatocellular carcinoma (HCC) by cDNA microarray, we found that KIF23 was upregulated in HCC tissues." (PMID 26674738, 2015). "Among other regulators of cytokinesis, KIF23 expression was shown to be upregulated in non-small cell lung cancer and hepatocellular carcinoma." (PMID 23650552, 2013). "It has also been reported that PRC1 controls the expression and function of wrrag such as FANCI, SPC25, KIF11, and KIF23 via Wnt signaling in hepatocellular carcinoma (HCC)." (PMID 40400636, 2025). "Based on these findings, a potential miR-497-mRNA or miR-1246-mRNA regulatory network can be established, namely, miR-497-ARL2/UBE2Q1/PHF19/APLN/CHEK1/CASK/SUCO/CCNE1/KIF23, or miR-1246-AUTS2/SLAIN1, which contributes to the occurrence and development of hepatocellular carcinoma." (PMID 34163524, 2021).
non-small cell lung carcinoma (8 papers, 2012 to 2023). A group of at least three distinct histological types of lung cancer, including non-small cell squamous cell carcinoma, adenocarcinoma, and large cell carcinoma. "Overexpression of KIF23 in non-small cell lung cancer (NSCLC) governs the crucial functions of KIF23 in regulating the cancerous properties of the cells." (PMID 32365332, 2020). "KIF23 was also up-regulated with three other genes in non-small cell lung cancer." (PMID 22956898, 2012). "Besides, p.P916R mutation of KIF23 causes a rare hereditary form of dyserythropoietic anemia (CDA III) with predisposition to blood cancer, and they further demonstrated that overexpression of KIF23 in non-small-cell lung cancer might be caused by CNAs." (PMID 34017355, 2021).
liver cancer (6 papers, 2020 to 2025). An epithelial or non-epithelial malignant neoplasm that arises from the liver. "Pathogenic conditions associated with aberrant expression of ODF2L, MAST2 and KIF23 include ciliopathy, liver cancer and chronic myeloid leukemia, respectively." (PMID 37026480, 2023). "In mice, hydrodynamic tail vein injection of pre-miR-107 or anti-Kif23 shRNA effectively inhibited c-Myc-NRAS-induced aggressive liver cancer, highlighting miR-107/KIF23 as a potential therapeutic target." (PMID 40546347, 2025). "KIF23 plays an important role in the process of mitosis, which is closely related to the occurrence and development of liver cancer." (PMID 33148251, 2020). "High KIF23 expression correlates with poor prognosis in liver cancer." (PMID 40546347, 2025).
ovarian carcinoma (6 papers, 2020 to 2022). A malignant neoplasm originating from the surface ovarian epithelium. "It is suggested that the decrease in miR-424-5p can enhance the expression of KIF23 and inhibit the proliferation and migration of ovarian cancer cells." (PMID 35409396, 2022).
cervical cancer (5 papers, 2017 to 2026). A primary or metastatic malignant neoplasm involving the cervix. "Targeting the KIF23/MYH9/MCM2/PCNA axis sensitises cervical cancer cells to cisplatin." (PMID 41940421, 2026). "Furthermore, overexpression of KIF23 has been shown to promote malignant phenotypes by accelerating cell proliferation and inhibiting pyroptosis, thereby facilitating tumor progression of cervical cancer." (PMID 41138746, 2025). "A research showed an increase of KIF23 levels in preinvasive CIN 1 and invasive cervical cancer." (PMID 29312619, 2017).
prostate carcinoma (5 papers, 2020 to 2025). A carcinoma that arises from epithelial cells of the prostate gland. "AURKA, AURKB, and KIF23 were predictive biomarkers of prostate cancer progression, and upregulation of these genes was associated with promotion of cell-cycle progression." (PMID 41024516, 2025).
bladder cancer (4 papers, 2019 to 2025). "Studies have shown that KIF14 and KIF23 are aberrantly expressed in bladder cancer." (PMID 40062654, 2025). "Cell and animal experiments confirmed the link between KIF23 and bladder cancer." (PMID 35669725, 2022).
lung adenocarcinoma (4 papers, 2019 to 2025). A carcinoma that arises from the lung and is characterized by the presence of malignant glandular epithelial cells. "Depletion of KIF23 is also suggested as another potential cancer therapeutic approach for lung adenocarcinoma." (PMID 33747961, 2021). "KIF23 depletion inhibits tumor formation by inducing apoptosis in certain types of cancer, such as lung adenocarcinomas." (PMID 31695969, 2019). "KIF23, a mitotic kinesin, was previously characterized as an MMB target gene important for tumorigenesis in an oncogenic K-RAS-driven mouse model of lung adenocarcinoma." (PMID 33747961, 2021).
melanoma (4 papers, 2013 to 2025). A malignant, usually aggressive tumor composed of atypical, neoplastic melanocytes. "Melanoma cells derived from metastatic lesions patients also found KIF23 mutation by whole-exome sequencing and SNP array profiling." (PMID 34017355, 2021). "MUC19, PAICS, RBMXL1, KIF23 have been identified in melanoma, which might deserve further investigations the role in cancer." (PMID 28159935, 2017). "We also identified mutations in four genes (MUC19, PAICS, RBMXL1, KIF23) never reported in melanoma, which might deserve further investigations." (PMID 23704925, 2013). "Similarly, KIF23 mRNA levels were found to be higher in cancers, such as bladder, CNS tumors, breast, cervical, colorectal, esophageal, gastric, head and neck, liver, lung, lymphoma, melanoma, ovarian, pancreatic, and sarcoma compared to normal tissues, as depicted in Fig. (4B)." (PMID 39248068, 2025).
pancreatic ductal adenocarcinoma (4 papers, 2021 to 2025). An infiltrating adenocarcinoma that arises from the epithelial cells of the pancreas. "In pancreatic ductal adenocarcinoma, overexpression of KIF23 predicts poor prognosis." (PMID 35524313, 2022).
dyserythropoietic anemia (3 papers, 2021 to 2025). "CDA‐III is the rarest subtype of dyserythropoietic anemia, usually inherited as an autosomal dominant disorder due to mutations in the KIF23 gene that codes for Mitotic Kinesin‐Like Protein 1 (MKLP1), a centralspindlin component important for cytokinesis." (PMID 40927401, 2025). "Other very rare types of CDA are caused by autosomal dominant mutations in KIF23 (Kinesin Family Member 23, CDA type III), KLF1 (Kruppel-Like Factor 1, CDA type IV) or X-linked mutations in GATA1 (GATA Binding Protein 1, X-linked thrombocytopenia with or without dyserythropoietic anemia)." (PMID 33672223, 2021).